SIRT3 (sirtuin 3)
Diseases named in the same sentence as SIRT3 in open-access papers (continued):
Sharing a sentence is not in itself a finding about the gene and the disease.
gestational diabetes mellitus (4 papers, 2019 to 2023). "In gestational diabetes, upregulated SIRT3 enhanced autophagy activation by promoting the AMPK-mTOR pathway and decreasing GPX4 levels to induce ferroptosis in trophoblastic cells." (PMID 34869322, 2021). "In addition, our previous study showed that SIRT3 mRNA expression was decreased in postpartum women with gestational diabetes mellitus and T2D." (PMID 30736780, 2019). "Moreover, the resistance observed in cases of SIRT3 deficiency to autophagy-dependent ferroptosis induced by high glucose and erastin implies that targeting SIRT3 might hold promise as a therapeutic approach for the treatment of gestational diabetes mellitus (GDM)." (PMID 38041059, 2023).
idiopathic pulmonary fibrosis (4 papers, 2021 to 2024). Idiopathic pulmonary fibrosis (IPF) is a nonneoplastic pulmonary disease that is characterized by the formation of scar tissue within the lungs in the absence of any known cause. "Similarly, in a model of idiopathic pulmonary fibrosis (IPF), lung-fibroblast-derived EVs were able to increase mitochondrial ROS and cause mitochondrial damage via miR-23b-3p and miR-494-3p, which suppress SIRT3 expression." (PMID 36671550, 2023).
infarction (4 papers, 2019 to 2025). A localised pathological necrosis of tissue resulting from obstruction of the blood supply usually by a thrombus, an embolus, or vascular torsion. "The treatment of hearts with DHM significantly decreased infarction size and improved cardiac function, but this effect was inhibited by Sirt3 knockout." (PMID 31139646, 2019). "AMPK-Drp1 axis is involved in Sirt3-mediated attenuation of cardiac injury after infarction." (PMID 35602095, 2022).
lentivirus infection (4 papers, 2018 to 2025). Virus diseases caused by the Lentivirus genus. "Sirt3 inhibition by 3‐TYP or Sirt3 silencing by lentivirus infection both confirmed the impaired cementogenesis." (PMID 40068967, 2025). "The Western blot results showed that the AAV-SIRT3 lentivirus infection successfully established SIRT3-overexpressed SW620 and HT29 cell lines." (PMID 34747319, 2022). "Further, Sirt3‐silenced cells were constructed by lentivirus infection and successfully identified." (PMID 40068967, 2025). "We established a SIRT3 stable overexpression cell line using lentivirus infection in SH-SY5Y cells." (PMID 29896416, 2018).
lipid metabolism disorders (4 papers, 2015 to 2024). "In our previous studies, we found that mitochondrial lipid metabolism disorders occurred in the hypertrophic myocardium of SIRT3 knockout (SIRT3−/−) mice." (PMID 38625851, 2024). "Combined with the results observed in SIRT3-deficient mice, we speculated that lipid metabolism disorders during hypertrophy are due to a loss of deacetylation function caused by a lack of SIRT3." (PMID 25748450, 2015). "Thus, under normal conditions, the lower concentration of fatty acid may not exceed the FAO capacity and arouse lipid metabolism disorders, even in the SIRT3-KO mice." (PMID 25748450, 2015).
periodontal disease (4 papers, 2021 to 2025). "The present study assessed the functional role of SIRT3 in age‐related periodontal disease and the underlying mechanisms." (PMID 34591326, 2021). "This study aimed to investigate the functional role of SIRT3 in age‐related periodontal disease and underlying mechanisms." (PMID 34591326, 2021). "The current study was designed to investigate the functional role of SIRT3 in the pathogenesis of age‐related periodontal disease and to explore underlying mechanisms." (PMID 34591326, 2021). "Recently, it was found that reduced SIRT3 abundance in mice can exacerbate age-related periodontal disease." (PMID 36238549, 2022). "Reduced SIRT3 abundance contributes to aged‐related periodontal disease via the exacerbation of oxidative stress and mitochondrial dysfunction." (PMID 34591326, 2021). "The regulation of ROS by SIRT3 and ROS‐induced damage could be important mechanisms by which SIRT3 influences aging and the age‐related periodontal disease." (PMID 34591326, 2021). "As age increased, we observed a decline of protein abundance of SIRT3 in alveolar bone (Figure 1A1‐A2), which was accompanied with an increased protein acetylation modification, suggesting that SIRT3 may play a role in the pathogenesis of age‐related periodontal disease." (PMID 34591326, 2021). "However, the role of SIRT3 in periodontal disease remains unknown." (PMID 34591326, 2021). "In periodontal diseases, although not directly, some sirtuins (SIRT4- and SIRT3-families) are studied, and there tend to be associations with various pathologies, such as diabetes melitus." (PMID 35630070, 2022). "The evidence indicates that CypD can be deacetylated by SIRT3, resulting in an inhibited mPTP opening, but whether SIRT3 regulates CypD involved in the pathogenesis of periodontal disease has not been evaluated." (PMID 34591326, 2021).
small cell lung carcinoma (4 papers, 2022 to 2023). Small cell lung cancer (SCLC) is a highly aggressive malignant neoplasm, accounting for 10-15% of lung cancer cases, characterized byrapid growth, and early metastasis. "Sirtuin 3 (SIRT3), which is related to AC236972.3, can inhibit the proliferation of human small-cell lung cancer cells by promoting apoptosis and necroptosis." (PMID 35938013, 2022). "Other Bcl-2 proteins are also regulated by Sirt3; thus, in NCI-H446 human small-cell lung cancer cells, the proapoptotic Bid level was elevated and the antiapoptotic Mcl-1 level decreased." (PMID 35938164, 2022).
thyroid cancer (4 papers, 2015 to 2020). "miR-1225-5p was downregulated in thyroid cancer, which inhibited the malignant phenotype of thyroid cancer cells by regulating SIRT3." (PMID 33336045, 2020).
Arterial thrombosis (3 papers, 2018 to 2021). The formation of a blood clot inside an artery. "Moreover, ex vivo LPS-induced NETosis was increased in Sirt3−/− bone marrow-derived neutrophils, indicating that SIRT3 deletion in the inflammatory environment affected NETosis and arterial thrombosis in mice." (PMID 33680285, 2021). "We confirmed that IS-induced arterial thrombosis after chronic administration increased the kinetics and strength of clot formation, and contributed to platelet hyperactivity as well as reduced aortic levels of SIRT1 and SIRT3." (PMID 30546314, 2018). "This study demonstrates that IS promotes arterial thrombosis and prothrombotic state that is connected with an increased level of complex TF/VII, PAI-1, and platelet activation, as well as decreased aortic contents of SIRT1 and SIRT3." (PMID 30546314, 2018).
asthma (3 papers, 2022 to 2024). "Consistent with animal data, Sirt1, Sirt3, and Sirt5 expression was decreased in the peripheral blood of patients with asthma compared to controls." (PMID 38135684, 2023). "Additionally, NMN has been reported to attenuate airway epithelial barrier dysfunction by inhibiting SIRT3 SUMOylation in asthma models." (PMID 39857368, 2024). "This is the only searchable study about the function of SIRT3 in asthma to date." (PMID 36117172, 2022). "Further research is needed on the relationship between SIRT3 and asthma." (PMID 36117172, 2022).
atrial fibrillation (3 papers, 2022 to 2025). A disorder characterized by an electrocardiographic finding of a supraventricular arrhythmia characterized by the replacement of consistent P waves by rapid oscillations or fibrillatory waves that vary in size, shape and timing and are accompanied by an irregular ventricular response. "Enhancing SIRT3 expression can reverse the metabolic remodeling of atrial muscle induced by atrial fibrillation." (PMID 40710369, 2025).
candidiasis (3 papers, 2017 to 2022). Infection with the organism Candida. "Additionally, SIRT3+/+ and SIRT3−/− mice behaved roughly identically following systemic infection with L. monocytogenes and C. albicans given to produce chronic/mild and acute candidiasis." (PMID 28634345, 2017).
cholangiocarcinoma (3 papers, 2019 to 2026). A carcinoma that arises from the intrahepatic biliary tree (intrahepatic cholangiocarcinoma) or from the junction, or adjacent to the junction, of the right and left hepatic ducts (hilar cholangiocarcinoma). "SIRT3, downregulated in cholangiocarcinoma (CCA) patients, can prevent tumor progression by inhibiting the HIF1α/PDK1/PDHA1 pathway." (PMID 35136826, 2022).
chronic myelogenous leukemia (3 papers, 2016 to 2025). "Kaempferol treatment increased the expression and the mitochondria localization of the SIRT3 in chronic myelogenous leukemia cell K562." (PMID 27367026, 2016). "Recently, it has been suggested that KMP could increase the expression of Sirt3 in chronic myelogenous leukemia cells." (PMID 40835924, 2025). "Interestingly, it has earlier been shown that basal but not enhanced autophagy activity regulates UPS mediated Sirt3 degradation in chronic myeloid leukemia cells." (PMID 32092124, 2020).
disc degeneration (3 papers, 2018 to 2024). "For the in vivo experiments, our study showed that HKL treatment attenuated puncture-induced rat disc degeneration, with higher levels of SIRT3 in the rat NP." (PMID 30420619, 2018). "We found that the expression level of SIRT3 in NP samples decreased with the degree of disc degeneration." (PMID 30420619, 2018).
hepatic (3 papers, 2020 to 2023). "During hepatitis B virus (HBV) infection, nuclear SIRT3 was recruited to the HBV covalently closed circular DNA (cccDNA) to inhibit cccDNA transcription by regulating cccDNA-bound histone acetylation H3." (PMID 37789393, 2023).
Hyperinsulinemia (3 papers, 2018 to 2022). An increased concentration of insulin in the blood. "Silent information regulation 2 homolog 3 (SIRT3) was overexpressed to evaluate the effect of hyperinsulinemia on the metabolic switch to BHB absorption and utilization through the SIRT3/SMCT1 pathway in HK2 cells." (PMID 36237185, 2022). "Moreover, hyperinsulinemia inhibits the absorption of BHB through the inhibition of the SIRT3/SMCT1 pathway." (PMID 36237185, 2022). "We observed higher weight gain, hyperinsulinemia hypertriglyceridemia and elevated circulating CRP in western diet-fed Sirt3−/− mice." (PMID 30510203, 2018).
hypothyroidism (3 papers, 2021 to 2022). Abnormally low levels of thyroid hormone. "In the present study, we sought to investigate the effect of the RBP4/PiC/SIRT3 signaling pathway on mPTP opening in rats that suffered from hypothyroidism during pregnancy." (PMID 33503180, 2021). "SIRT3 expression in rats with maternal hypothyroidism during pregnancy at P35 was significantly higher than that in normal controls." (PMID 33503180, 2021). "In summary, our findings demonstrate that the activation of the RBP4/PiC/SIRT3 signaling pathway could be involved in the regulation of the opening/closing of the renal mPTP in rats that develop maternal hypothyroidism during pregnancy." (PMID 33503180, 2021). "Moreover, the RBP4/PiC/SIRT3 pathway was identified to be involved in the function of the renal mPTP of offspring rats with hypothyroidism during pregnancy." (PMID 33503180, 2021). "However, SIRT3 expression in rats with maternal hypothyroidism during pregnancy at P35 was lower than that at P14." (PMID 33503180, 2021). "However, SIRT3 expression in the CON group was significantly higher than that in the hypothyroidism group." (PMID 33503180, 2021).
intrahepatic cholangiocarcinoma (3 papers, 2018 to 2022). A carcinoma that arises from the intrahepatic bile duct epithelium in any site of the intrahepatic biliary tree. "In intrahepatic cholangiocarcinoma, TUG1 acts as a ceRNA that sponges miR-145 to prevent the degradation of sirtuin 3 (Sirt3) mRNA." (PMID 36499136, 2022).
male infertility (3 papers, 2023 to 2025). The inability of the male to effect fertilization of an ovum after a specified period of unprotected intercourse. "Targeting SIRT3 represents a promising therapeutic strategy for improving boar fertility and may also provide insights for research into human male infertility." (PMID 41148848, 2025). "In addition, lower levels of sirtuins such as SIRT1 and SIRT3 in seminal plasma or within sperm can exacerbate damage to sperm DNA, thus making it unfit for proper fertilization, leading to male infertility." (PMID 38255792, 2024). "Notwithstanding these limitations, our work identifies SIRT3 activation as a promising therapeutic strategy to ameliorate storage-induced damage and improve boar fertility and may also provide insights for research into human male infertility." (PMID 41148848, 2025). "Hence, it can be concluded that lower seminal plasma levels of SIRT1, SIRT3, TAC, SOD and catalase may result in increases in oxidative stress, which impacts on various sperm parameters, thereby leading to male infertility." (PMID 38255792, 2024).
mantle cell lymphoma (3 papers, 2019 to 2022). Mantle cell lymphoma is a rare form of malignant non-Hodgkin lymphoma affecting B lymphocytes in the lymph nodes in a region called the ``mantle zone''. "Interestingly, lower Sirt3 protein expression was associated with worse OS in mantle cell lymphoma (MCL) patients." (PMID 31010244, 2019). "Lower SIRT3 protein expression was associated with poorer OS in mantle cell lymphoma (MCL) patients." (PMID 36497259, 2022).
multiple sclerosis (3 papers, 2012 to 2024). A progressive autoimmune disorder affecting the central nervous system resulting in demyelination. "Many Sirt-3-related pathologies show different incidences, onsets and/or progression between sexes, such as PD, AD, multiple sclerosis, cardiovascular diseases, and many cancer types." (PMID 38612678, 2024).
neuropathic pain (3 papers, 2022 to 2025). Chronic pain caused by damage to nerve fibers. "In the neuropathic pain and inflammatory pain model, SIRT3 depletion induces mitochondrial antioxidant enzyme dysfunction and thus increased oxidative stress." (PMID 38572816, 2024). "In this study, we found that the protein and mRNA levels of SIRT3 were significantly downregulated in the spinal cords of spared nerve injury- (SNI-) induced neuropathic pain mice, while overexpression of spinal SIRT3 reversed SNI-induced pain hypersensitivity." (PMID 36092157, 2022).
overnutrition (3 papers, 2018 to 2025). An imbalanced nutritional status resulting from excessive intake of nutrients. "In addition, mice models with SIRT3-deletion or SIRT3-manipulation showed that the associated dysfunction appeared to be specific to the type of metabolic stress, for example, it failed to affect insulin secretion or β cell metabolism in the absence of overnutrition." (PMID 36902123, 2023).
prostate tumor (3 papers, 2015 to 2025). "Furthermore, the renal capsule model also showed that SIRT3 overexpression suppressed the prostate tumor formation." (PMID 26317998, 2015). "In this study, we report that SIRT3 could act as a prostate tumor suppressor through inhibition of the PI3K/Akt pathway, resulting in ubiquitination and degradation of oncoprotein c-MYC." (PMID 26317998, 2015).
psoriasis (3 papers, 2021 to 2023). An autoimmune condition characterized by red, well-delineated plaques with silvery scales that are usually on the extensor surfaces and scalp. "In order to further establish a causal link between SIRT3 and XBP1s in psoriasis, we performed a rescue experiment by pharmacologically decreasing XBP1s level with MKC8866." (PMID 37275851, 2023). "This discovery highlights the role of SIRT3 deficiency in psoriasis, and mitophagy mediated by SIRT3 may be a new therapeutic target for psoriasis treatment." (PMID 37445960, 2023). "Subsequently, we found that SIRT3 mRNA of macrophages from 30 patients with psoriasis decreased compared to paired healthy volunteers." (PMID 37275851, 2023). "We found that SIRT3 was decreased in both T cells and monocytes derived from patients with psoriasis compaired to healthy volunteers, and the difference was more significant in monocytes." (PMID 37275851, 2023). "In the present study, we found that SIRT3 was essential for modulating psoriasis-like inflammation and was downregulated in psoriatic macrophages." (PMID 37275851, 2023). "In conclusion, the deacetylation function of SIRT3 targeting XBP1s represents a new regulatory mechanism in inflammation and provides a latent target for treating psoriasis." (PMID 37275851, 2023). "SIRT3 deficiency exacerbated the TLR7/8-XBP1s response via deacetylation activity targeting XBP1s, contributing to the transcription of proinflammatory cytokines IL-23, IL-6, and TNF-α and thus promoting psoriasis progression and disease severity." (PMID 37275851, 2023). "Inhibition or knockdown of SIRT3 could exacerbate psoriasis-like skin inflammation in an imiquimod-induced psoriasis-like mouse model." (PMID 37275851, 2023). "Here, we focused on the deacetylation activity of SIRT3 in the UPR in psoriasis." (PMID 37275851, 2023). "Besides, a decrease in SIRT3 expression was observed in the macrophages of psoriasis patients, which increased the expression and acetylation level of XBP1s." (PMID 37275851, 2023). "In contrast, SIRT3 overexpression activates parkin-dependent mitophagy through deacetylation of the traction factor FOXO3a to eliminate inflammation, oxidative stress and excessive cell proliferation in psoriasis." (PMID 37445960, 2023). "Our findings indicate that suppressing SIRT3 exacerbated IMQ-induced psoriasis-like inflammation by upregulating the levels of acetylated XBP1s, which subsequently enhanced its total protein levels and transcriptional activity and increased the production of IL-23a, IL-6, and TNF-α cytokines." (PMID 37275851, 2023). "In order to probe the expression of SIRT3 in T cells and monocyes, we isolated CD3+ T cells and CD14+ monocytes from PBMCs of 10 patients with psoriasis and age- and sex-matched healthy volunteers via flow cytometry cell sorting technology." (PMID 37275851, 2023). "There is a significant reduction in the expression of SIRT1, SIRT2, SIRT3, SIRT4 and SIRT5 and an increase in the expression of SIRT6 and SIRT7 in psoriasis." (PMID 37445960, 2023). "Besides, SIRT3 governs the production of IL-23 and TNF-α, dominant cytokines in the pathological processes in psoriasis, endowing SIRT3 with higher status in psoriasis than in other inflammatory diseases." (PMID 37275851, 2023). "We constructed IMQ-induced psoriasis-like mouse models with Sirt3-/- mice to rule out putative unspecific effects of pharmacological inhibitors." (PMID 37275851, 2023). "To verify the functional relevance of SIRT3 upregulation or downregulation in the development of psoriasis, we inhibited or activated SIRT3 activity pharmacologically with 3-TYP or Honokiol and then constructed an IMQ-induced psoriasis mouse model." (PMID 37275851, 2023). "We hypothesized that SIRT3 diminished TLR7/8-XBP1s response and thereby ameliorated inflammation in psoriasis." (PMID 37275851, 2023).
psoriasis (continued). "The dysregulation of this auto-regulatory loop could be also due to the abnormal expression of SIRTs in psoriasis, with the downregulation of SIRT1, SIRT2, SIRT3, SIRT4, and SIRT5 and upregulation of SIRT6 and SIRT7 in skin lesions skin, as previously reported." (PMID 34202251, 2021).